ALB (albumin)
Diseases named in the same sentence as ALB in open-access papers (continued):
Sharing a sentence is not in itself a finding about the gene and the disease.
Sepsis (continued). "Further-more, albumin is a transport carrier of cholesterol and other molecules, likely affecting the fluctuation in fatty acids and outcomes in sepsis." (PMID 36832250, 2023). "Existing studies have shown that both Hematocrit (HCT) and albumin (ALB) can be used as potential predictors of sepsis, and their difference HCT-ALB has a significant capacity to diagnose infectious diseases." (PMID 35850582, 2022). "Hypoalbuminemia is common in critically ill patients and often causes a poor prognosis, with previous studies suggesting a correlation between serum ALB level and sepsis patient prognosis." (PMID 35850582, 2022). "Previous studies have shown that low serum albumin level at sepsis presentation is a strong predictor of septic shock." (PMID 36494633, 2022). "NGS and ALB were found to be the independent factors for sepsis in a multi-factor logistic regression analysis." (PMID 36189371, 2022). "The lactate/albumin ratio is a good prognostic marker for predicting in-hospital mortality in sepsis patients." (PMID 36197158, 2022). "In a recent study, albumin and CRP were indicated as risk factors that independently affect 28-day mortality in sepsis patients over 65 years of age (p<.001)." (PMID 36465747, 2022). "Although ALB and NGS alone were insufficient to diagnose sepsis, diagnostic efficiency was significantly improved when combined (p<0.05)." (PMID 36189371, 2022). "Third, sepsis patients have a hypermetabolic and hypercatabolic state, increasing the catabolism of ALB." (PMID 35109818, 2022). "In cases of hepatorenal syndrome, as well as in those with severe sepsis and septic shock, intravenous human albumin is given either on its own or in combination with vasoactive medications." (PMID 36721617, 2022). "NM administration significantly decreased the plasma contents of AST, ALT, and DBIL, while increasing the ratio of ALB to GLB compared to the sepsis control." (PMID 35345558, 2022). "The CAR has recently been considered as a more useful indicator of sepsis than CRP or albumin alone." (PMID 35887857, 2022). "Sepsis patients with lower VDBP serum level had lower ALB and TP, as well as higher APCHE II and SOFA scores, suggesting the negative association of VDBP level and sepsis disease severity." (PMID 35057868, 2022). "Another retrospective study concluded that in sepsis, the probability of survival decreased by 63.4% when serum albumin was ≤ 2.45 g/dl on admission, and by 76.4% when the lowest serum albumin during hospitalization was ≤ 1.45 g/dl." (PMID 36528689, 2022). "The current consensus was that the benefit of albumin in improving the prognosis of patients with sepsis relative to crystalloids remained unclear, which was consistent with our results." (PMID 35721190, 2022). "According to the Surviving Sepsis Campaign Guidelines for the Treatment of Sepsis and Septic Shock and other Sepsis Guidelines, crystalloids are the first choice, and albumin is recommended as a safe addition when crystalloids alone are insufficient." (PMID 36430652, 2022). "It has been reported that serum albumin is a strong predictor of mortality in elderly patients with sepsis." (PMID 36591285, 2022). "Although we used the most distinguishing attributes to analyze organ function, other attributes, including ABG, electrolytes, albumin, shock index, and hemoglobin, are also crucial in analyzing various aspects of the health status of sepsis patients." (PMID 36812596, 2022). "In our study, after adjusting for other risk factors for sepsis in relation to COVID-19, CURB-65, d-dimer, and HO-1 remained significant risk factors, and albumin was a protective factor for sepsis." (PMID 36464717, 2022). "In our cohort of patients with early sepsis at the ED, however, albumin levels were in the lower normal range (20–49 g/dL)." (PMID 35624664, 2022).
Sepsis (continued). "We constructed a new nomogram to predict the risk of ICU p-LOS in obesity patients with sepsis using seven risk factors (maximum WBC, minimum WBC, use of ventilation, GCS, minimum albumin, maximum respiratory rate, and minimum RDW)." (PMID 36033731, 2022). "Previous studies have shown that the lactate/albumin ratio at admission can independently predict the mortality of patients with severe sepsis or septic shock." (PMID 35685488, 2022). "The most recent Surviving Sepsis Guidelines also suggest using albumin in patients with sepsis who have received large volume crystalloid resuscitation." (PMID 36329266, 2022). "Recently, there have been many studies on the relationship between albumin and fibrinogen levels and sepsis prognosis." (PMID 35990041, 2022). "As such, LDH to albumin ratio was introduced as new independent, composite prognostic factor for patients’ survival in severe infections, such as sepsis but also in those with COVID-19." (PMID 36614820, 2022). "Research is also warranted on the role of glycosylated hemoglobin (HbA1c) and glycated albumin in predicting the outcomes of sepsis." (PMID 35248158, 2022). "Previous literature has demonstrated that BUN is a reliable prognostic biomarker of sepsis, and albumin is negatively correlated with sepsis." (PMID 36407534, 2022). "The premorbid ambulation ability with albumin and C-reactive protein can be combined to predict 28-day mortality in elderly patients with sepsis." (PMID 35962331, 2022). "Studies have confirmed that human serum albumin can achieve an ideal effect in the treatment of sepsis." (PMID 35559342, 2022). "Significant contributions were made by age, gender, heart rate, sepsis, albumin level, and mean arterial pressure." (PMID 36544226, 2022). "A decreased albumin/globulin ratio (A/G ratio) was recently reported as a novel independent predictor of the development of postflexible ureteroscopic sepsis." (PMID 35704364, 2022). "This study investigated the prognostic value of the albumin-to-fibrinogen ratio (AFR) in patients with sepsis as a consequence of infection at various sites." (PMID 35990041, 2022). "The levels of CREA, PCT and CRP in sepsis groups were higher than those of the non-sepsis group, while the level of ALB was lower (p<0.05)." (PMID 36189371, 2022). "Albumin is the preferred colloid in sepsis, as fluid resuscitation with albumin is less likely to cause nephrotoxicity than with artificial colloids." (PMID 36337861, 2022). "Albumin is the most abundant protein in human plasma, and patients with sepsis frequently have hypoalbuminemia." (PMID 36577937, 2022). "Inflammation elicited by trauma (surgical or otherwise) or acute disease (sepsis, pancreatitis) is the most important condition leading to decreased serum albumin levels." (PMID 33875388, 2022). "The Surviving Sepsis Campaign Guidelines recommended that septic patients with substantial crystalloid input used albumin to maintain stable arterial pressure during initial resuscitation." (PMID 36337861, 2022). "The half-life of serum albumin is 19 days, and it varies accordingly in acute and chronic illnesses, sepsis, and injuries." (PMID 36589182, 2022). "Independent predictors of SVDD include age, gender, sepsis, postoperation, season, heart rate, mean arterial pressure, and albumin level." (PMID 36544226, 2022). "This is relevant, as many other factors common in the SCT and post-SCT course influence albumin levels, e.g., hydration and sepsis." (PMID 34932150, 2022). "The effect of albumin on the occurrence of cardiac complications is seldom described in patients with sepsis." (PMID 36337861, 2022). "Several studies have evaluated the validity of the ratio of lactate to albumin (LAR) as a predictor in diseases such as infectious shock or severe sepsis and cardiac arrest." (PMID 36591285, 2022).
Sepsis (continued). "In contrast, patients with sepsis who experienced 28-day mortality exhibited significantly lower levels of albumin, AFR, and pH than those who survived beyond 28 days." (PMID 35990041, 2022). "Regardless, the role of hypernatremia in sepsis has recently become increasingly accepted; the use of balanced crystalloids or albumin instead of 0.9% saline during fluid resuscitation in sepsis is also more appreciated." (PMID 36140385, 2022). "We also included BMI and sepsis in the final model, regardless of the Wald test result, because BMI (a basic nutrition factor) and sepsis have critical effects on albumin that influence in-hospital mortality." (PMID 35672868, 2022). "In contrast, patients with sepsis had significantly lower PLT, lymphocyte (Ly), alkaline phosphatase (ALP), albumin (ALB) levels than patients with non-sepsis (p < 0.05, all of them)." (PMID 35864446, 2022). "In sepsis and acute illness, the albumin transcapillary escape rate is increased, and the synthesis rate in the liver is increased to a lesser extent, resulting in an altered distribution over fluid compartments and decreased serum albumin." (PMID 35235196, 2022). "The CTP score uses more clinically significant parameters (albumin, bilirubin, PT, and ascites) than the MELD score (bilirubin, INR) to predict the endoscopy-associated sepsis, which makes using the CTP score for prediction more favorable." (PMID 35139804, 2022). "Patients who underwent fURS compared to PNL or have certain pre-operative characteristics, such as albumin <35 g/L and positive urine culture, are more likely to develop post-operative sepsis." (PMID 35495750, 2022). "Because of these roles, previous studies have reported that the serum albumin level is a predictor of outcomes of critically ill patients with conditions such as sepsis and myocardial infarction." (PMID 36579497, 2022). "A study performed in sepsis found lower levels of platelets, white blood cells, albumin, and total protein in the CytoSorb® group." (PMID 35788557, 2022). "In the South Korean population, the ALB level was independently negatively correlated with mortality in sepsis patients with AKI undergoing CRRT." (PMID 35109818, 2022). "The Lactate-to-Albumin Ratio (LAR) has been applied as a new predictor in sepsis, heart failure, and acute respiratory failure." (PMID 36591285, 2022). "The latest sepsis guidelines recommend the use of albumin for patients undergoing massive crystalloid resuscitation, but there is no recommendation for CS." (PMID 35694666, 2022). "However, in sepsis, the vascular permeability is increased since the glycocalyx and endothelium are damaged or dysfunctional, but evidence showed that the albumin might protect against the loss of glycocalyx and reduce its damage in shock models, therefore, decreasing the fluid leakage." (PMID 35495750, 2022). "Recently, LAR, calculated by the ratio of lactate to albumin in human serum, is widely used as a prognostic indicator in patients with various critical illnesses, such as cardiac arrest, sepsis, and trauma." (PMID 36324387, 2022). "As expected, prognostic biomarkers of sepsis, such as the albumin level, PT, A/G ratio, total protein level, and cholesterol level, ranked high." (PMID 35704364, 2022). "In patients with sepsis aged 18 years and older, albumin/CRP ratios at admission and discharge were better predictors of 90-day and 180-day mortality after hospitalization compared to albumin or CRP alone." (PMID 35235196, 2022). "The levels of albumin, an abundant circulating protein in plasma, can be reduced during sepsis and critical illnesses due to decreased synthesis, increased breakdown, as well as increased vascular permeability, leading to leakage of this protein." (PMID 36262941, 2022).
Sepsis (continued). "(including 1136 patients with an AUC of 0.869 for LAR, 0.816 for lactate, and 0.812 for albumin) results for sepsis studies showed that LAR was a better predictor of in-hospital mortality than the use of lactate or albumin alone." (PMID 36591285, 2022). "In the present study, we observed that the area under the ROC curve of RAR was superior to that of RDW or albumin alone, suggesting that RAR has a higher predictive value for 28-d morbidity and mortality in sepsis patients than RDW or albumin alone." (PMID 36211519, 2022). "ALB was independently negatively correlated with mortality in sepsis patients with AKI undergoing CRRT." (PMID 35109818, 2022). "This study was mainly based on blood urea nitrogen to albumin ratio (B/A), a comprehensive index, to explore its correlation with the prognosis of sepsis patients during hospitalization." (PMID 36577937, 2022). "AFR consists of albumin and fibrinogen, which are widely used as prognostic factors in patients with sepsis." (PMID 35990041, 2022). "Following the ALBIOS and SAFE trial, the surviving sepsis authors recommend including albumin as the resuscitative colloid of choice." (PMID 36555895, 2022). "This retrospective cohort study aimed to investigate the association between red blood cell distribution width-to-albumin ratio (RAR) and in-hospital mortality in patients with sepsis and atrial fibrillation (AF)." (PMID 36494633, 2022). "As compared to sham-operated animals, septic shock was always associated with significantly lower albumin values, and the animals in the sepsis subgroup also showed temporarily lower albumin values during t = 16–24 h of the study." (PMID 35615093, 2022). "Analytical specificity and selectivity of the DETecT Sepsis 2.0 device was evaluated by cross‐reactivity study using bovine serum albumin (BSA) in whole blood buffer matrix." (PMID 36176597, 2022). "Except for operation type, other variables have been reported to be independent risk factors for sepsis after PNL or fURS, such as staghorn calculi, positive midstream urine culture, stone size, and albumin–globulin ratio (AGR)." (PMID 35495750, 2022). "Previous studies have shown that lactate/albumin ratio (LAR) can be used as a prognostic biomarker to independently predict the mortality of sepsis and severe heart failure." (PMID 34407102, 2021). "Due to its long half-life (14–20 days), albumin is a marker of chronic malnutrition, although its level can be affected by dehydration, sepsis, trauma, liver disease, and albumin replacement." (PMID 33805775, 2021). "The levels of laboratory indices, including white blood cell count, haemoglobin level, haematocrit, platelet count, albumin level, aspartate aminotransferase level, and creatinine level, were significantly worse in the sepsis patients compared to the NC group." (PMID 34429344, 2021). "In fact, according to the results of previous studies in patients suffering from inflammation, sepsis, head injury, or burns albumin synthesis rates have been shown to be increased." (PMID 34920728, 2021). "There is a robust body of evidence evaluating the effects of albumin administration in critical illness in general and, more specifically, in sepsis and septic shock, either as a primary comparison or as a subset analysis of a larger trial." (PMID 33644843, 2021). "More prospective multi-center studies are needed in the future to further clarify the benefits of early albumin combined with crystal fluid rehydration in the treatment of patients with sepsis." (PMID 33689042, 2021). "The levels of Scr, CRP and WBC were increased but the level of albumin was decreased in sepsis patients relative to healthy controls (P < 0.001)." (PMID 34126975, 2021). "Low preoperative albumin and hematocrit, dyspnea, preoperative use of steroids, and preoperative sepsis were predictors of 30-day morbidity on univariate analysis." (PMID 35096617, 2021).
Sepsis (continued). "Serum protein and albumin levels exhibited depressed level during acute episode of sepsis but recovered at three months." (PMID 34869619, 2021). "In a prespecified subgroup analysis of patients with severe sepsis in the SAFE trial, the use of 4% albumin was associated with a lower adjusted risk of death compared with isotonic saline." (PMID 34040918, 2021). "To date, there is still insufficient evidence to demonstrate the better beneficial effect of albumin than crystalloids in fluid administration for sepsis." (PMID 33689042, 2021). "In conclusion, the data presented here suggest that the oxidation status of albumin in patients with sepsis is related to the time of exposure to oxidative stress (differences between day 1 and day 7)." (PMID 34447316, 2021). "Further clinical trials with S. albumin correction (target serum conc. of 3 gm/dl) as intervention can be safely tried in melioidosis patients presenting with sepsis." (PMID 34285680, 2021). "This trial was a multicenter, randomized, open label comparison of 20% albumin and crystalloid compared to crystalloid alone in 1,818 adults with sepsis or septic shock." (PMID 33718468, 2021). "In a post hoc anslysis of ALBIOS study, albumin replacement added to crystalloid showed more hemodynamic stability than crystalloid alone, in patients with severe sepsis and septic shock." (PMID 34943582, 2021). "In a basic study, pigs with hepatic injury and sepsis were treated with a blood purification system using circulating albumin dialysate." (PMID 33557434, 2021). "In a Danish population-based study in 1844 patients with community-acquired bacteremia, a single plasma albumin measurement on the date bacteremia was identified was a better predictor of short-term mortality than a sepsis severity score." (PMID 33925831, 2021). "It should be noted that the timeliness of albumin combined in fluid administration for sepsis is essential, a longer deferred combination indicated the less improved outcomes." (PMID 33689042, 2021). "In the univariate Cox proportional model used for analyzing 1-year mortality, age, albumin, number of RBC transfusion units, and sepsis were risk factors for mortality after LT." (PMID 34462528, 2021). "Albumin is considered appropriate when used in the context of sepsis and septic shock after crystalloid therapy is given first." (PMID 34613990, 2021). "This has resulted in a suggestion from SSC to use albumin in addition to crystalloids for initial resuscitation and subsequent intravascular volume replacement in patients with sepsis and septic shock when patients require substantial amounts of crystalloids." (PMID 33644843, 2021). "As a matter of fact, low serum albumin is a mortality predictor in critically ill patients with sepsis and septic shock." (PMID 34683480, 2021). "Ebenfalls keinen Mortalitätsvorteil zeigte die randomisierte, offene „Volume-replacement-with-albumin-in-severe-sepsis“(ALBIOS)-Studie 9, die der SAFE-Studie folgte." (PMID 34618163, 2021). "The top indications for which albumin was administered were sepsis or septic shock (25.3%), hypotension or hypovolemia (19.4%), intra-dialytic hypotension (13.4%), fluid support in surgery (10.8%), and nephrosis or nephropathy (10.8%)." (PMID 34613990, 2021). "The individual responses regarding albumin use for infections/sepsis, hyponatremia, renal impairment, and encephalopathy were heterogeneous." (PMID 33270161, 2021). "Albumin was used appropriately in the 47 patients presenting with sepsis or septic shock, the 36 patients presenting with hypotension or hypovolemia, and the 20 patients presenting with nephrosis or nephropathy." (PMID 34613990, 2021). "This is a first report describing the relationship between the circulating concentrations of albumin and fibrinogen and their respective synthesis rates in sepsis." (PMID 34920728, 2021). "The albumin concentration in sepsis patients was lower than that in the control individuals (P < 0.001)." (PMID 34784841, 2021).